SPATS1 (spermatogenesis associated serine rich 1)
Synonyms: SPATA8; FLJ25442; SRSP1; DDIP
Tractability: No criterion of Open Targets' tractability assessment is met for any kind of drug.
Gene: Protein-coding gene on chromosome 6 (44,342,650 to 44,380,179, forward strand). Ensembl gene ENSG00000249481.
Subcellular location (Human Protein Atlas): Nucleoplasm
Gene Ontology:
Molecular function: protein binding
Genetic constraint (gnomAD): Loss-of-function variants: 17 observed, 28.23 expected, observed/expected ratio (o/e) 0.6, 90% interval 0.41 to 0.9. The upper end of that interval is the gene's LOEUF score, 0.9, which puts it in group 3 of 6, group 1 being the genes least tolerant of losing a copy. Missense variants: 287 observed, 339.88 expected, observed/expected ratio (o/e) 0.84, 90% interval 0.77 to 0.93. Synonymous variants: 121 observed, 123.39 expected, observed/expected ratio (o/e) 0.98, 90% interval 0.85 to 1.14.
Homologues: Orthologues: chimpanzee SPATS1 (96% identical), dog SPATS1 (79% identical), macaque SPATS1 (69% identical), pig SPATS1 (67% identical), mouse Spats1 (59% identical), rat Spats1 (58% identical), guinea pig SPATS1 (51% identical).
Diseases named in the same sentence as SPATS1 in open-access papers:
SPATS1 is named in the same sentence as 7 diseases in open-access papers, as found by Europe PMC text mining. Sharing a sentence is not in itself a finding about the gene and the disease. The quoted sentences say what the papers report.
Infertility (1 paper, 2021). "If this were the case for Spats1, it could possibly reconcile the discrepancies between the lack of phenotype of Spats1 KO mice, and the reports that associate alterations or polymorphisms of Spats1 with human male pathologies such as infertility and testicular cancer." (PMID 33945571, 2021).
male infertility (1 paper, 2021). The inability of the male to effect fertilization of an ovum after a specified period of unprotected intercourse. "Some reports have suggested a link between SPATS1 underexpression/mutation and human pathologies such as male infertility and testicular cancer." (PMID 33945571, 2021).
testicular cancer (1 paper, 2021). A primary or metastatic malignant neoplasm that affects the testis. "Furthermore, an exome-wide sequencing study has proposed a possible association between Spats1 mutation and the development of human seminomas, which are the most common type of testicular cancers." (PMID 33945571, 2021).
SPATS1 also shares sentences with these, for which no sentence is quoted: Bell's palsy (1 paper); cancer (1); colon cancer (1); meningioma (1).